RNU7-61P (RNA, U7 small nuclear 61 pseudogene)
Synonyms: U7.61
Gene: Small nuclear RNA gene on chromosome 16 (30,483,135 to 30,483,195, reverse strand). Ensembl gene ENSG00000251706.
Homologues: Orthologues: chimpanzee U7 (100% identical), macaque U7 (95% identical). Paralogues in human: RNU7-21P (92% identical), RNU7-25P (90% identical), RNU7-26P (90% identical), RNU7-14P (89% identical), RNU7-27P (89% identical), RNU7-3P (89% identical), RNU7-7P (89% identical), RNU7-8P (89% identical), RNU7-19P (87% identical), RNU7-20P (87% identical), RNU7-28P (87% identical), RNU7-2P (87% identical), and 143 more.